TPPP (tubulin polymerization promoting protein)
Diseases named in the same sentence as TPPP in open-access papers (continued):
Sharing a sentence is not in itself a finding about the gene and the disease.
Atrophy (1 paper, 2019). Any weakening or degeneration, especially through lack of use. "Individuals with spastic paraplegiamay present with atrophy of the spinal cord and defects in the upper limbs.These results indicate that SLC6A3, CCT5 and TPPP showimportant connection." (PMID 30985858, 2019).
Autoimmunity (1 paper, 2021). The occurrence of an immune reaction against the organism's own cells or tissues. "The colocalization of MANF with the mature oligodendrocyte cell body marker TPPP was not affected by treatment with dex indicating that dex only increased MANF-levels in myelinated axons, the primary targets of autoimmunity in EAE." (PMID 34305531, 2021).
coenzyme Q10 deficiency (1 paper, 2014). A genetically heterogeneous condition, typically inherited in an autosomal recessive fashion, characterized by coenzyme Q10 deficiency. "Although only one case was available for the present analysis, these results demonstrate that the COQ2 mutation, leading to Coenzyme Q10 deficiency, causes TPPP relocation." (PMID 25208467, 2014).
hepatocellular carcinoma (1 paper, 2024). A malignant tumor that arises from hepatocytes. "The low TPPP expression indicated a poor prognosis in hepatocellular carcinoma." (PMID 38893499, 2024).
lung adenocarcinoma (1 paper, 2015). A carcinoma that arises from the lung and is characterized by the presence of malignant glandular epithelial cells. "CNVs with low amplification (TPPP and SLC6A18) and undefined biological function (LOC100506688) were excluded from further studies on the associations between target CNVs and lung adenocarcinoma prognosis." (PMID 26497366, 2015).
ovarian tumors (1 paper, 2020). "In contrast to the issue presented in relation of TPPP/p25, higher mRNA and/or protein expression of TPPP3 was found in tumor cells in comparison to normal ones in most cases investigated up to now, for example, in various lung, colorectal and ovarian tumors and in HeLa cells." (PMID 32033023, 2020).
prion disease (1 paper, 2011). A transmissible disease that is caused by a protein that is able to induce abnormal folding of normal cellular proteins, leading to characteristic spongiform brain changes, which are associated with neuronal loss without an inflammatory response. "Whether TPPP involves in the normal functions of PrP or the pathogenesis of prion disease remains unknown." (PMID 21857997, 2011). "However, whether TPPP is able to form complex with PrP and what its contributions to physiological functions of PrPC and pathogenesis of prion disease are remain unsettled." (PMID 21857997, 2011).
scrapie (1 paper, 2011). A fatal disease of the nervous system in sheep and goats, characterized by pruritus, debility, and locomotor incoordination. "It suggests that deposits of PrPSc in brains of scrapie experimental hamsters cause a marked decrease of endogenous TPPP at their final stage of clinical courses." (PMID 21857997, 2011). "A significantly decreased endogenous TPPP in the brains of scrapie experimental animals has been proposed in this study, which corresponds well the previous observation of lower levels of endogenous tubulin in the brain tissues of scrapie-infected hamsters." (PMID 21857997, 2011). "Compared with that of the health control, the intensities of PrP specific blots were greatly high while that of TPPP-specific signals were extremely low in the preparations of scrapie infected animals." (PMID 21857997, 2011). "Quantitative analyses of the relative gray values of the immunoblot images after equilibrated with that of β-actin identified significantly increased PrP and decreased TPPP in the brains of scrapie infected hamsters, compared with that of normal one (P<0.05)." (PMID 21857997, 2011). "Moreover, the levels of the endogenous TPPP in the brains of scrapie-infected experimental hamsters were significantly decreased." (PMID 21857997, 2011). "Furthermore, Western blots identified that the levels of the endogenous TPPP in the brains of scrapie-infected experimental hamsters were significantly reduced." (PMID 21857997, 2011).
Senile plaques (1 paper, 2021). Senile plaques are extracellular deposits of amyloid in the gray matter of the brain. "In particular, it was applied to the detection of Aβ and tau aggregates, neurofibrillary tangles, and cerebral amyloid angiopathy; assessment of dendritic spines and accumulation of senile plaques; evaluation of the development of TPPP/p25 aggregates in patients with AD." (PMID 34436057, 2021).
testicular cancer (1 paper, 2025). A primary or metastatic malignant neoplasm that affects the testis. "TPPP was previously shown to be associated with testicular cancer." (PMID 40358182, 2025).
cancer (7 papers, 2008 to 2024). A tumor composed of atypical neoplastic, often pleomorphic cells that invade other tissues. "The importance of some of the genes of this region (TERT, CLPTM1L) were verified, but the relationship of TPPP/p25 to malignant tumors remains to be clarified." (PMID 32033023, 2020). "In exploring a potential cancer therapy, we found that TPPP has an anti-proliferative action." (PMID 38391951, 2024). "It was suggested that amplification of TPPP/p25 may confer a growth advantage to cancerous cells due to the abnormalities in tubulin assembly and spindle formation that are common features in malignant tumors." (PMID 32033023, 2020). "Likewise, TPPP was found to be associated with several cancers; however, no insights into its role in cancer were described either." (PMID 30149579, 2018). "Thus, understanding the role of TPPP/p25 in cell division might open a new perspective in cancer research." (PMID 18644768, 2008).
neurodegenerative disease (5 papers, 2015 to 2025). A disorder of the central nervous system characterized by gradual and progressive loss of neural tissue and neurologic function. "TPPP/p25 is a microtubule-associated protein, detected in protein inclusions associated with various neurodegenerative diseases." (PMID 26289831, 2015). "In summary, developing successful therapies requires the identification and validation of the distinct pathomechanisms of neurodegenerative diseases, taking into account the potency of TPPP as a pathological partner." (PMID 38391951, 2024). "A new relationship emerged between OGA levels and tubulin polymerization-promoting protein (TPPP), a protein involved in tubulin stabilization and has been linked to neurodegenerative diseases." (PMID 35248135, 2022). "This pathological interaction between the two PPDPs has implications for the identification of new biomarkers for neurodegenerative diseases where, in the case of MSA and PD, we propose using both the SYN and TPPP levels and/or the ratio of SYN to TPPP in the CSF." (PMID 38391951, 2024). "The non-physiological level of TPPP/p25 may lead to distinct disorders, either to cancerous or to neurodegenerative diseases (and references therein)." (PMID 32033023, 2020).
tumor (5 papers, 2019 to 2024). "The lower mRNA and/or protein expression of TPPP/p25 occurs much more frequently in the case of tumor cells in comparison to normal ones." (PMID 32033023, 2020). "Our analysis identified seven tumour suppressor genes (ITGA7, SLC45A1, TPPP, SCN4A, GIPR, SOGA3 and RAB6B) and six oncogenes (SAT1, SERPINE1, UPK2, SYT12, RASAL1 and CDH3) with significant false discovery rate (FDR)-adjusted P values (q-value) of less than 0.05." (PMID 38429478, 2024).
neurological disorders (4 papers, 2014 to 2025). "In the last decade, however, Tubulin Polymerization Promoting Protein (TPPP) has also emerged as one of the principal actors in the processes underlying neurological disorders." (PMID 38391951, 2024). "The pathological SYN-TPPP/p25 interaction is coupled with the loss of the physiological function of TPPP/p25 such as the modulation of the dynamics and stability of the microtubule network leading to neurological disorders." (PMID 35163473, 2022).
TPPP also shares sentences with these, for which no sentence is quoted: Alzheimer disease (3 papers); Parkinsonism (3); diabetes (2); neuroblastoma (2); amyotrophic lateral sclerosis (1); Anxiety (1); Astrocytoma (1); Barrett's oesophagus (1); bladder cancer (1); colorectal cancer (1); gastric cancer (1); kidney disease (1); liver cancer (1); memory impairment (1); oesophageal adenocarcinoma (1); ovarian carcinoma (1); prostate carcinoma (1); Proteopathies (1).